MCL1 (MCL1 apoptosis regulator, BCL2 family member)
Diseases named in the same sentence as MCL1 in open-access papers (continued):
Sharing a sentence is not in itself a finding about the gene and the disease.
metastatic tumors (12 papers, 2009 to 2024). "When combined with conventional chemotherapy agents, this MCL1 inhibitor showed strong anti-tumor activity in mice with established metastatic disease, even eliminating detectable disease in some mice." (PMID 37676378, 2024). "We also found that MCL1 was transcribed more in metastatic tumors than the primary tumor." (PMID 37676378, 2024). "Co-treatment with cyclophosphamide further improved the efficacy of the MCL1-specific BH3 mimetic AZD5991, reducing and even eliminating detectable metastatic disease in mice." (PMID 37676378, 2024). "Mcl-1 was elevated in primary PCa with high Gleason grades and metastatic tumors compared to that in prostatic intraepithelial neoplasia (PIN) or lower grade tumors, suggesting a pivotal role of Mcl-1 in PCa progression." (PMID 20085644, 2010). "Simultaneous disruption of both BCL-2 and MCL-1 via small-molecule inhibitors induces robust regression of tumors in a SS PDX model and cell-line xenograft model as well as multiple cell lines derived from both primary and metastatic disease." (PMID 34065859, 2021). "Lastly, case OVA_378 presented a single shared actionable MCL1 amplification between its primary and metastatic tumour, with no additional actionable genes specific to either primary HGSOC, or its corresponding distant metastasis." (PMID 32099096, 2020). "In principle, a combination of a BH3 mimetic, such as BI-97D6 with more pronounced Bcl-2/Mcl-1 inhibitory activity, with a CRCA such as Ad.tCCN1-CTV-m7 expressing a systemically active cytokine, mda-7/IL-24, should elicit profound efficacy toward both primary and metastatic tumors in the clinic." (PMID 25926554, 2015).
sarcoma (12 papers, 2006 to 2025). A usually aggressive malignant neoplasm of the soft tissue or bone. "Genetic and pharmacological inhibition of MCL1 induces rapid apoptosis in CIC::DUX4 sarcoma cells and inhibits tumor growth in a xenograft model." (PMID 40841513, 2025). "A panel of human sarcoma cell lines were used to validate the observed decrease of MCL-1 in the rat fibrosarcoma cell line and to determine if the in vitro findings translated to human sarcomas and potentially to patients." (PMID 27783991, 2016). "The level of MCL-1 decreased substantially with GLV-1h68 therapy alone in the human sarcoma cell lines and showed a further decrease when combined with EBRT." (PMID 27783991, 2016). "Thus, MCL1 represents a potential therapeutic target for CIC::DUX4 sarcoma." (PMID 40841513, 2025). "We found remarkably depressed levels of the endogenous MCL-1 inhibitor, NOXA, in SS compared to other sarcomas." (PMID 34065859, 2021). "In the human sarcoma cell lines, the anti-apoptotic proteins MCL-1 and BCL-XL were not affected by EBRT alone." (PMID 27783991, 2016). "As the differential expression of anti-apoptotic proteins (e.g., MCL-1 or BCL-XL) or pro-apoptotic proteins (e.g., BIM, PUMA, or NOXA) can alter sensitivity to BCL-2 inhibition, we evaluated the expression of BCL2 family transcripts across multiple sarcoma tumor types." (PMID 34065859, 2021). "MCL-1 is expressed in a variety of different human sarcoma cell lines, and MCL-1 antisense oligonucleotides combined with low-dose cyclophosphamide provides a synergistic anti-tumour effect, and may qualify as a promising strategy to overcome chemoresistance in human sarcoma." (PMID 20003259, 2009). "Finally, expression of other anti-apoptotic proteins such as Mcl-1 and Bcl-XL did not vary after FVP treatment in any sarcoma cell line tested." (PMID 29757258, 2018).
follicular lymphoma (11 papers, 2013 to 2024). Follicular lymphoma is a form of non-Hodgkin lymphoma characterized by a proliferation of B cells whose nodular structure of follicular architecture is preserved. "On C1D1, maximal MCL1 mRNA inhibition occurred at 1–2 hours postdose except for patient with the transformed follicular lymphoma, which was observed at 8 hours postdose." (PMID 37882668, 2023). "Recent studies have shown that the overexpression of USP9X in follicular lymphoma correlates with increases in levels of the anti-apoptotic protein MCL1 and poorer prognosis." (PMID 23667531, 2013).
head and neck squamous cell carcinoma (11 papers, 2013 to 2025). A squamous cell carcinoma that arises from any of the following anatomic sites: lip and oral cavity, nasal cavity, paranasal sinuses, pharynx, larynx, and salivary glands. "Metformin-mediated down-regulation of this protein did not appear to be only caused by global translational inhibition, as observed for Mcl-1 in metformin-treated head and neck squamous cell carcinoma cell lines, since Mcl-1 reduction was associated with increased Noxa expression." (PMID 26265439, 2015). "Overexpression of antiapoptotic proteins such as BCL2, BCL2L1/BCL-XL, and MCL1, on the other hand, negatively correlates with response to cisplatin in ovarian or head and neck squamous cell carcinoma (HNSCC) patients." (PMID 34645978, 2021). "Hypertonicity-induced functional loss of MCL-1 renders BCL-XL a synthetically lethal target in head and neck squamous cell carcinoma (HNSCC), and inhibiting BCL-XL efficiently kills HNSCC cells that respond poorly to conventional therapies." (PMID 37612282, 2023). "Mcl-1 is reported to be regulated by the miR-204 microRNA in head and neck squamous cell carcinoma (HNSCC), where it behaves as a tumor suppressor." (PMID 24025188, 2013). "A recent finding demonstrated that co-inhibition of MCL-1 and BCL-XL was feasible in a zebrafish model of head and neck squamous cell carcinoma and embryonic chicken model of rhabdomyosarcoma (RMS)." (PMID 35201512, 2022).
metastatic melanoma (11 papers, 2008 to 2018). A melanoma that has spread from its primary site to another anatomic site. "Effects caused by silencing of Bcl-2, Bcl-xL, Bcl-w, Mcl-1, or A1 were analyzed in the metastatic melanoma cell line 1205Lu." (PMID 22292048, 2012). "We have found that depletion of β-catenin results in reduced expression of the anti-apoptotic proteins Mcl-1 and Bcl-xl showing the relevance of β-catenin for cell survival of metastatic melanoma cells." (PMID 21858114, 2011). "Complicating an antisense strategy, Bcl-2 expression may also be reduced in metastatic melanoma, and other antiapoptotic Bcl-2 proteins such as Mcl-1 or Bcl-xL may substitute for Bcl-2." (PMID 19506730, 2008). "In addition, transcript GCSM011, which is located near the known oncogene MCL1, was associated with significantly decreased survival rate (p value 0.0002, Χ2 test, FDR < 0.005), marked by a 25% decrease in survival after five years with metastatic melanoma." (PMID 29284497, 2017). "Each of the primary and metastatic melanoma cell lines used in our study showed unique anti-apoptotic protein (e.g., BCL2, BCL-xL and/or MCL-1) expression signature that related with their response to BH3-mimetics." (PMID 29348439, 2018). "We evaluated pretreatment mRNA expression of BCL-2 family members, BCL-2, MCL-1, BCL-XL, BCL-W, BIM, and BID in tumors of patients with metastatic melanoma." (PMID 24983357, 2014). "Since Bcl2 expression was lower in metastatic melanoma than in benign nevi and Bclxl and Mcl-1 were overexpressed in metastatic melanoma, Bcl2 may not be an optimal anti-apoptotic protein to target in melanoma." (PMID 24281185, 2010).
cardiomyopathy (10 papers, 2017 to 2025). A disease of the heart muscle or myocardium proper. "Ckmm-Cre mediated deletion of Mcl-1 caused fatality within 10 days post-birth with evidence of rapid and fatal cardiomyopathy, including thinning of the heart walls, cardiac dilation, thrombus deposition, and interstitial fibrosis." (PMID 34336857, 2021). "This toxicity can be due to the relevant role of Mcl-1 in cardiac homeostasis in adult murine models, loss of Mcl-1 causing alterations in cardiomyocytes and lethal cardiomyopathy." (PMID 32455818, 2020). "Meanwhile, in inducible cardiac-specific Mcl1 knockout mice, Mcl1 loss rapidly causes cardiomyopathy and death." (PMID 33469534, 2020). "It has been shown that “cardiac-specific deletion of MCL-1 in mice” led to mitochondrial dysfunction, impaired autophagy, hypertrophy, and cardiomyopathy with distorted ultrastructure of disorganized sarcomeres and swollen mitochondria." (PMID 37601693, 2023). "Conditional knockout of MCL1 in cardiomyocytes in mice induces rapid cardiomyopathy and death." (PMID 34475520, 2021). "MCL-1 had previously been shown to be important for normal tissue physiology, including cardiac homeostasis, with early studies demonstrating cardiomyocyte-specific Mcl-1 knockout in mice resulting in the development of a rapid and fatal cardiomyopathy due to mitochondrial swelling and rupture." (PMID 34073507, 2021). "Whilst the co-deletion of both Bax and Bak rescued the cardiomyopathy associated with the loss of Mcl-1, it did not reverse the mitochondrial abnormalities in cardiac muscles." (PMID 34336857, 2021). "MCL-1 plays a critical role in normal physiology, including cardiomyocyte mitochondrial homeostasis, and MCL-1 knockout in mice induces fatal cardiomyopathy, highlighting the challenge of identifying a therapeutic window for this target." (PMID 35008216, 2021).
gallbladder cancer (10 papers, 2016 to 2024). "For example, MALAT1 functioned as a competing endogenous RNA to regulate MCL-1 expression by sponging miR-363-3p in gallbladder cancer." (PMID 30683807, 2019). "MALAT1 functions as a competing endogenous RNA to regulate MCL-1 expression by sponging miR-363-3p in gallbladder cancer." (PMID 29212230, 2017). "To explore the role of MCL‐1 in gallbladder cancer progression, we next measured the expression levels of MCL‐1 by qRT‐PCR." (PMID 27420766, 2016). "Therefore, the effect of MALAT1 on gallbladder cancer cell proliferation is due, in part, to its function as a molecular sponge of miR‐363‐3p that targets MCL‐1." (PMID 27420766, 2016). "The MALAT1/miR‐363‐3p/MCL‐1 regulatory network may be a novel therapeutic target for gallbladder cancer." (PMID 27420766, 2016). "Previously we found that Mcl-1 expression is increased in gallbladder carcinoma tissues." (PMID 26848531, 2016). "In gallbladder cancer, lncRNA MALAT1 has been documented to function as a ceRNA to negatively modulate MCL-1 expression by sponging miR-363-3p." (PMID 32760216, 2020).
head and neck cancer (10 papers, 2014 to 2025). A primary or metastatic malignant neoplasm affecting the head and neck. "Increased phosphorylated STAT3 and Mcl-1 have been often associated with poor prognosis and poor outcome response to chemo- and radiotherapy in various tumors, including head and neck cancer, and inhibition of STAT3 is known to block cancer cell proliferation." (PMID 25605256, 2015). "It suppressed the mTORC1/myeloid cell leukemia 1(Mcl-1) pathway to promote apoptosis in head and neck cancer cells." (PMID 35527284, 2022). "In head and neck cancer models CFZ resistance was associated with increased levels of the Bcl-2 family member, Mcl-1." (PMID 25612802, 2014). "Medical subject headings keywords for Mcl-1, along with its other identifiers, and head and neck cancers (only oral cavity tumors) were used to evaluate the expression, function, molecular association, and therapeutic approach of Mcl-1 in oral cavity cancers and precancers." (PMID 35524332, 2022). "Indeed, a recent publication has shown that NPC, an epithelial head and neck cancer associated with EBV that expresses high levels of BCL‐2 in 80% of cases, can be efficiently treated by a combination of ABT‐199 and S63845, an MCL‐1 inhibitor." (PMID 32623836, 2020).
mesothelioma (10 papers, 2011 to 2024). A usually malignant and aggressive neoplasm of the mesothelium which is often associated with exposure to asbestos. "In mesothelioma, overexpression of BCL-2 was found in 20% of cell lines and in 24% of a tumor samples, while the expression of BCL-XL and MCL-1 was identified as a general feature of mesothelioma, suggesting their critical role as pro-survival factors." (PMID 34249695, 2021). "Citrate leads to an early decrease in the expression of the anti-apoptotic protein Mcl-1, a molecule that plays a key role together with the protein Bcl-xL in the chemoresistance of certain cancers, particularly mesothelioma." (PMID 31307409, 2019). "A second anti-apoptotic protein, MCL1, is also expressed in mesothelioma, and together with Bcl-xL, can further inhibit apoptosis and confer resistance to mesothelioma." (PMID 29342862, 2018). "In fact, it has been suggested that one of the important reasons able to confer to mesothelioma its strong resistance to chemotherapy is the overexpression of anti-apoptotic proteins of the Bcl-2 family (such as Bcl-xL and Mcl-1 protein)." (PMID 27806086, 2016). "In our previous study using the NCI-H226 spheroid model, we demonstrated an increase of Mcl-1 in mesothelioma spheroids compared to monolayers, indicating that the mesothelioma spheroid model acquired Bcl-2 signaling apoptotic resistance." (PMID 22737246, 2012). "Cafestol and kahweol modulated the promoter activity and protein expression level of the Sp1 regulatory genes including Cyclin D1, Mcl-1, and Survivin in mesothelioma cells." (PMID 22734486, 2012). "In the present study, we demonstrated an increase of Mcl-1 in spheroids as compared to monolayers, indicating that the 3D mesothelioma spheroid model had acquired Bcl-2 signaling apoptotic resistance as well as multicellular resistance." (PMID 21305058, 2011). "A significant decrease in MCL1 expression was observed after treatment with HSP90 inhibitors in vitro and in explants from mesothelioma and this correlated with sensitivity to ganetespib." (PMID 26096930, 2016).
oral squamous cell carcinoma (10 papers, 2015 to 2025). "MCL-1 stabilisation by JOSD1 has also been implicated in conferring radioresistance in oral squamous cell carcinoma (OSCC) wherein TRAF4 mediates MCL-1 phosphorylation, making it inaccessible for JOSDI interaction." (PMID 39284830, 2024). "Mcl-1 is a target protein of Specificity protein 1 (Sp1) and panobinostat downregulates via Sp1 suppression in oral squamous cell carcinoma." (PMID 33806487, 2021). "This study initially explored the essential role Mcl-1 played and the regulatory effect of Ras-Erk pathway in anti-cancer process triggered by tubulin inhibitor, broadening clinical horizon of tubulin inhibitors in oral squamous cell carcinoma chemotherapy application." (PMID 35002504, 2022). "The results of immunohistochemical analysis unveiled that, among the 52 oral squamous cell carcinoma cases examined, 42.3% (22/52) and 44.2% (23/52) showed high expressions of p-EGFR and Mcl-1, respectively." (PMID 38888847, 2025). "In the case of oral squamous cell carcinoma, the E3 ligase TRAF4 activates Akt through the ubiquitination pathway, inhibits GSK3β activity and MCL-1 phosphorylation, and enhances the regulatory effects of the DUB JOSD1 on MCL-1." (PMID 38137461, 2023).
rhabdomyosarcoma (10 papers, 2015 to 2025). A rare aggressive malignant mesenchymal neoplasm arising from skeletal muscle. "We show here Mcl-1 upregulation in response to S63845 treatment alone, as also reported previously in breast, colon, rhabdomyosarcoma, and T-ALL tumor cell lines." (PMID 38542429, 2024). "A synergistic effect of combined ERK1/2 and MCL-1 inhibition was also seen in rhabdomyosarcoma cell lines." (PMID 37108344, 2023). "In conclusion, our findings indicate that the combination of a BH3 mimetic targeting MCL-1 with trametinib improves efficiency on rhabdomyosarcoma by blocking tumor adaptation to treatment." (PMID 35393436, 2022). "Indeed, we found that the MCL-1 inhibitor S63845 synergistically enhanced trametinib cytotoxicity in rhabdomyosarcoma cells in vitro and in vivo." (PMID 35393436, 2022).
squamous cell carcinoma (10 papers, 2008 to 2023). A carcinoma arising from squamous epithelial cells. "Somatic FBW7 mutation in squamous cell carcinoma cells is associated with stabilized Mcl-1 and high Bim levels, resulting in a poor response to standard chemotherapy, but a robust response to HDAC inhibitors and enhanced synergy with the combination vorinostat/ABT-737." (PMID 26405162, 2015). "The treatment of squamous carcinoma cells with vorinostat regulates the expression of Bcl-2 family members and suppresses Mcl-1, a major and tissue-specific survival factor in squamous cell carcinoma, thereby inducing apoptosis." (PMID 34001246, 2021). "Furthermore, despite concomitant upregulation of NOXA and MCL1, squamous cell carcinomas retain sensitivity to ABT-737 due to an increased NOXA:MCL1 ratio." (PMID 26910119, 2016). "For instance, MCL-1 inhibitor sabutoclax (BI97C1) and COX-2 inhibitor celecoxib synergistically inhibits the growth of oral squamous cell carcinomas cells both in vitro and in vivo." (PMID 28659182, 2017). "Although Mcl-1 dominance renders squamous cell carcinoma cells resistant to ABT-737, the HDAC inhibitor vorinostat primes them for sensitivity to ABT-737 by shuttling Bim from Mcl-1 to Bcl-2/Bcl-xL, resulting in synergy for this drug combination and sustained tumor regression in vivo." (PMID 26405162, 2015).
thyroid cancer (10 papers, 2009 to 2024). "We have shown that in thyroid cancer cells sorafenib induces apoptosis by affecting Mcl-1 and Bcl-2 in BRAFV600E mutated cells which was independent of BRAF." (PMID 19878585, 2009). "However, two relatively sensitive cell lines (WRO82-1 and 8505C) had high basal levels of Mcl-1, raising the hypothesis that thyroid cancer cells that depend on Mcl-1 for survival may be susceptible to dinaciclib treatment." (PMID 28207834, 2017). "BCL-xL expression on the other hand was shown to be stronger in high-risk subtypes of thyroid carcinoma, while little is known about MCL1 expression in thyroid carcinoma tissues." (PMID 27042160, 2016). "With respect to the histological origin, there again was no obvious correlation of expression of the anti-apoptotic proteins BCL-2, BCL-xL and MCL-1 with thyroid carcinoma subtype of cell lines." (PMID 26198850, 2015). "Dinaciclib decreased Mcl-1, Bcl-xL and survivin levels in thyroid cancer cell lines." (PMID 28207834, 2017). "While some aspects of minority MOMP have been identified in mutant BRAF thyroid carcinoma, the role of Mcl-1 in this process is not well understood." (PMID 38622136, 2024).
diabetes (9 papers, 2014 to 2025). "In the early stages of diabetes, MCL-1 deficiency appears to contribute to β cell death." (PMID 37833817, 2023). "Interestingly, in humans, repression of MCL1 is related to diabetes mellitus-associated cardiomyocyte disorganization." (PMID 31683538, 2019). "Although this experimental study does not directly indicate an increased risk of developing T2DM associated with MCL1, it suggests that targeting the MCL1 gene could be beneficial in preventing the progression of diabetes, potentially offering new avenues for the treatment of diabetes." (PMID 40026415, 2025). "The role of MCL1 in diabetes mellitus needs to be characterized." (PMID 36051390, 2022). "Whether an up-regulation of miR-29 family miRNAs and suppression of MCL-1 (dysregulation of miR-29-MCL-1 axis) occurs in diabetic heart is not known." (PMID 25062042, 2014).